ITGA6 (integrin subunit alpha 6)
Diseases named in the same sentence as ITGA6 in open-access papers (continued):
Sharing a sentence is not in itself a finding about the gene and the disease.
cancer (195 papers, 2008 to 2026). A tumor composed of atypical neoplastic, often pleomorphic cells that invade other tissues. "ITGA6 is involved in the development of poor prognosis of aggressive cancer phenotypes, which can cause extracellular matrix modifications and antiapoptotic mechanisms in order to attain radio/chemoresistance." (PMID 37444576, 2023). "We showed that a high level of ITGA6 was overexpressed in cancer tissues and associated with a worse prognosis in HNC patients." (PMID 34307149, 2021). "ITGA6 is associated with an aggressive phenotype and radiation resistance in different types of cancers." (PMID 33255413, 2020). "ITGA6 expression levels were indeed associated with the presence of cancer stem-like cells, as well as with an invasive phenotype, with drug resistance and poor prognosis in a metastatic xenograft model." (PMID 26910918, 2017). "ITGA6 functions as an HPV receptor and has been linked to therapy resistance in HNSCC, making it an especially intriguing target in HNSCC In the cancer genome atlas (TCGA) dataset of HNSCC patients, ITGA3, ITGA5, and ITGA6 all show prognostic resolution." (PMID 40287842, 2025). "Many TME-related genes (such as VEGFA, MMP14, CCND1, MAP2K1, SLC2A1) and actin cytoskeleton-associated genes (such as ITGB4, ITGA6, ACTG1, VCL) were downregulated, suggesting a less favorable TME and an altered cytoskeleton network in ISO-treated cancer cells." (PMID 38339062, 2024). "Considering the fact that ITGB4, ITGA2, and ITGA6 were frequently up-regulated in cancer vs. normal tissues, our results suggest potential protumorigenic roles for them." (PMID 39436262, 2024). "Aberrant expression of the integrin ITGA6, for example, was shown to affect cell–matrix interactions and cancer progression by the regulation of various signaling pathways such as PI3K/AKT or MEK/ERK." (PMID 38672614, 2024). "Being readily detectable in more than 30 adult stem cells and cancer stem cells (CSCs), including glioblastoma, breast, colon, and prostate cancers, ITGA6 is present at low or undetectable levels in healthy tissues." (PMID 39329988, 2024). "One study revealed that the knockdown of the Twist2 gene suppressed the expression of ITGA6 and CD44, which are involved in the migration and invasion of cancer cells and are associated with the ECM–receptor interaction pathway." (PMID 38254353, 2024). "The importance of ITGA6 in the progression of a number of cancers, including hematological malignancies, suggests its potential usage as a novel prognostic or diagnostic marker and useful therapeutic target for better clinical outcomes." (PMID 37444576, 2023). "To date, ITGA6 was commonly found in more than 30 different populations of stem cells, including some cancer stem cells." (PMID 37255601, 2023). "Since then, more than 30 adult stem cells and cancer stem cells have been identified as displaying significant quantities of ITGA6." (PMID 37444576, 2023). "AKT is regarded as a primary mediator of resistance, and ITGA6 plays a crucial role in cancer resistance by modulating the MAPK/ERK and PI3K/AKT survival signaling pathways." (PMID 37444576, 2023). "Among the downstream genes, FN1, cadherin 2 (CDH2), EGFR, integrin subunit alpha 6 (ITGA6), and integrin subunit beta 4 (ITGB4), which are widely studied and are associated with cancer metastasis, were selected for further investigation." (PMID 37096833, 2023). "The role of ITGA6 differs based on several features, such as cell background, cancer type, and post-transcriptional alterations." (PMID 37444576, 2023). "The overexpression of ITGA6 indicates its potential use as a therapeutic target or for the development of novel combination therapeutic strategies to treat refractory cancers." (PMID 37444576, 2023). "TGF-β1 has also been linked to cancer cell invasion and to EMT in a variety of human cancers, and it is known to be regulated by ITGA6." (PMID 37444576, 2023).
cancer (continued). "ITGA6 is overexpressed in numerous types of malignancies, and its expression level is related to cancer development and poor survival in patients." (PMID 37444576, 2023). "The importance of ITGA6 in the progression of a number of cancers, including hematological malignancies, suggests its potential usage as a novel therapeutic target." (PMID 37444576, 2023). "The integrin α6 subunit (ITGA6) makes major contributions to colorectal cancer, hepatocellular cancer, and several other cancers, while also supporting stem-cell function in many cancers." (PMID 35624824, 2022). "ITGA6 is an oncogene in various cancers, including CC, where it is overexpressed and associated with proliferation and invasion." (PMID 35769999, 2022). "When ITGA6 forms α6β1 and α6β4 integrin complexes with other integrin subunits, embryogenesis, organogenesis, and cancer cell invasion can be mediated." (PMID 36057545, 2022). "As a transmembrane glycoprotein adhesion receptor protein, ITGA6 is widely upregulated in many types of tumors and plays a role in migration and invasion of cancer cell." (PMID 34220946, 2021). "Another member of the integrin family of proteins, ITGA6, has also been correlated with cell migration and invasion in cancer cells." (PMID 34366863, 2021). "The cellular and molecular examinations demonstrated a hub gene, ITGA6, that played prominent roles in cellular invasion and radioresistance, leading to refractory cancer." (PMID 34307149, 2021). "As a result, the upregulated ITGA6 protein promotes BlC cell adhesion, migration, and invasion, similar to multiple other types of cancer, in which ITGA6 overexpression promotes tumorigenesis and metastasis." (PMID 32404927, 2020). "In Caco-2 cells, LAD1 KD slightly reduced the mRNA expression of integrins such as ITGA2, ITGB1, and ITGA6, which are involved in cancer cell motility." (PMID 33267790, 2020). "IPA showed significant changes in the expression levels of genes associated with gastrointestinal disease (Abcb1, Guca2a, Muc2, Rag2, Itga6, and Shh), inflammatory disease (Abcb1, Muc2, and Rag2), and cancer (Muc2, Guca2a, and Rag2)." (PMID 33396408, 2020). "High MMP9 mRNA expression levels were associated with the expression of genes involved in cancer progression: BRCA2, COL4A1 and ITGA6, and were also associated with high FABP4 mRNA expression levels." (PMID 31874999, 2019). "Our results clearly identified MYC as an activator of both genes’ expressions because the endogenous MYC activation of the ITGA6 promoter in cancer cells was inhibited by the expression of the repressor domain of the dominant negative MAD." (PMID 29401653, 2018). "Among these genes, our previous studies demonstrated that ITGA3, ITGA6, and CAV2 were overexpressed in cancer tissues and associated with cancer cell migration and invasion." (PMID 28415821, 2017). "Studies targeting ITGA6 have demonstrated its strong potential to sensitize cancer cells to conventional radiotherapies in prostate and esophageal cancers." (PMID 27624978, 2016). "Integrin α6 (ITGA6), a transmembrane glycoprotein adhesion receptor protein, is widely upregulated in many types of tumors and promotes migration and invasion in cancer cells." (PMID 27624978, 2016). "The fact that both meta-A and meta-B gene sets share DEK, DUSP1 and ITGA6 in common indicates that all three cancer-related genes are more important to look at among all others." (PMID 18605998, 2008). "In addition, ITGA3, ITGA5, and ITGA6 show activating effects on the KEGG pathway in cancer, which is consistent with previous analysis results." (PMID 41602372, 2026). "In the mouse model dataset, TPCS cancer cells overexpress the luminal markers Xbp1 and Fgfr3 as well as the basal stem cell markers Itga6 and Cd44, the basal marker Egfr, and the EMT‐related marker Cldn4, suggesting that TPCS are of potential to generate multiple lineages." (PMID 38582099, 2024).
cancer (continued). "Lastly, it is necessary to further explore whether the SMAD3/ITGA6 signaling pathway has similar biological functions in other types of cancer." (PMID 38493128, 2024). "In this review, we summarized the recent understanding of ITGA6’s function in various cancer types." (PMID 37444576, 2023). "The ITGA6 may negatively regulate ECM‐induced PI3K‐AKT signalling thereby could suppress the survival of cancer cells." (PMID 38131168, 2023). "Therefore, ITGA6 can be proposed as a prognostic biomarker and therapeutic target in early-stage cancer diagnosis." (PMID 37444576, 2023). "In addition, immunohistochemical labeling from the Human Protein Atlas database revealed consistent ITGA6 protein levels in cancer cells." (PMID 37444576, 2023). "Recent studies have shown that ITGA6 is dysregulated in various types of cancer, including ccRCC." (PMID 37872217, 2023). "In the network, eight genes related to the apoptotic process and cell migration, including Mmp9, Cxcl12, Cdh1, Fap, Itga6, Mdk, Aif1, and Mif, were downregulated with co-treatment, which may play vital roles in inhibition of cancer progression and cell death." (PMID 36765032, 2023). "Several researchers have invented new ways to inhibit the growth of cancers by targeting ITGA6." (PMID 36268277, 2022). "Also, ITGA2, ITGA3 and ITGA6 are integrin coding genes that participate in cell adhesion, proliferation, and differentiation and are known to have anti-cancer properties in LC." (PMID 35600397, 2022). "Furthermore, we discovered that two other cancer stem cell-related genes, Cd44 and Itga6, were also significantly upregulated in the tumors." (PMID 33652981, 2021). "Clinically, ITGA6 has been reported altered expression in several cancers." (PMID 34307149, 2021). "Furthermore, in the cancer tissues, these genes were all statistically correlated with the expression of ITGA6." (PMID 34307149, 2021). "ITGB4, which forms a dimer with integrin α6 (ITGA6), has been widely studied in carcinomas." (PMID 34414684, 2021). "ITGA3 and ITGA6 were strongly expressed in several cancer tissues." (PMID 28415821, 2017). "Moreover, the gene microarray indicated knockdown of PSMC2 notably changed a number of genes, especially some cancer related genes including ITGA6, FN1, CCND1, CCNE2 and TGFβR2, and whose expression changes were further confirmed by western blotting." (PMID 27888613, 2017). "The 5-10 times increase in mRNA levels of ITGA6 in stools of patients with intestinal lesions may thus be attributed to the higher survival of exfoliated cancer and pre-cancer cells in the stools (and their mRNAs) as compared with normal cells." (PMID 26895101, 2016). "In addition to examining the added value of selecting cancer cells with a broader array of cytokeratins (CKs), they tested CD49f (ITGA6; integrin, alpha 6) as an alternative selection marker for CTC." (PMID 23401782, 2013). "Using ITGA6 as a biomarker for cancer invasiveness could be advantageous." (PMID 39329988, 2024). "Thus, further understanding of these mechanisms could unravel new therapeutic opportunities that specifically target ITGA6 in certain cells and cancer types, which could lead to better clinical outcomes." (PMID 37444576, 2023). "Finally, we used western blotting to detect the expression levels of several well-known key molecules in the cancer-associated signaling pathway so that we could investigate the regulatory mechanisms that link PSMC and /ITGA6 with HCC." (PMID 34413286, 2021). "Silencing ITGA6 may reverse radioresistance by sensitizing cancer cells to radiotherapy." (PMID 34307149, 2021). "Notably, ITGA6 is a cancer stem cell marker, also known as CD49f." (PMID 32806777, 2020). "Interestingly, many of the DMGs identified had multiple roles and several were potential cancer biomarkers or were previously shown to be implicated in various types of cancers, including ABLIM1, ADAM12, ARHGEF4, FBLN2, ITGA6, LRPAP1, Ly9, NT5E, PITPNC1, PLCG1, OBSCN, RHOH, SPTBN1, SPOCK2 and SPRY1." (PMID 41159936, 2025).
cancer (continued). "To verify this idea, we first analyzed the expression of CAVI, ITGA6, and ITGB4 in different BC cell lines in The Cancer Cell Line Encyclopedia database." (PMID 39494337, 2024). "The GSE20549 dataset reveals a positive correlation between SMAD3 and integrin subunit alpha 6 (ITGA6), a transmembrane glycoprotein adhesion receptor protein widely expressed in various tumors, known to facilitate cancer cell migration and invasion." (PMID 38493128, 2024). "Aberrant ERK signaling promotes cancer invasiveness, and GSCs rely on ERK signaling transduction to regulate the interaction between N-cadherin and ITGA6, thereby modulating GSC invasion in vitro." (PMID 39239559, 2024). "Human LAMC2 and ITGA6 are confirmed targets of miR-29 in cancer cells, where LAMC2 interacts with ITGA6 to improve focal adhesion formation and cell migration." (PMID 37981221, 2024). "TM4SF1 positive cancer cell subpopulation (TPCS) was characterized by the upregulation of TM4SF1, ITGA6, and KRT6A." (PMID 38582099, 2024). "Expression of ALDH1A1, ALPL, ITGA6, CD44, PROM1 (CD133), LGR5, and YAP1 upregulated in the E2 and E3 phenotypes was consistent with cancer hallmarks including cell plasticity, self-renewal, and drug-tolerant persistence." (PMID 38915538, 2024). "At the individual gene level, ITGA8 and ITGA9 were down-regulated in 11 out of the 15 cancers, whereas ITGAX, ITGB4, and ITGA6 were more frequently up-regulated in tumors relative to adjacent normal tissues (right)." (PMID 39436262, 2024). "Next, we identified significantly enriched KEGG (Pathways in cancer and PI3K/Akt signaling pathway) and GO (GO:0000122, GO:0045944 and GO:0045893) terms, and identified eight genes (EDN1, CCND1, MYB, MYC, RUNX1, ITGA6, IL6 and FGF2." (PMID 36978140, 2023). "This pancancer gene set includes key integrins (e.g. ITGA6, ITGB1, ITGB4) and their interconnectors (e.g. SPP1, TGFBI), affirming their critical role in the cancer adhesion resistome." (PMID 37206618, 2023). "The results indicated that the expression levels of TSC1, ITGA6, and MET in most cancer cell lines (SW1990, PANC1, Mia-paca-2, CFPAC1) were significantly higher than those in the normal cell line (H6C7)." (PMID 36261830, 2022). "Consistently, GPT2 KO decreased the expression of ITGA6, a HIF-induced integrin family member involved in cancer cell motility, in U251MG cells under 20% and 1% O2." (PMID 36010673, 2022). "qRT-PCR was performed to detect the relative expression levels of TSC1, ITGA6, and MET in normal and cancer cell lines." (PMID 36261830, 2022). "Thus, ITGA6 may serve as a predictive marker of radioresistance, a prognostic marker of metastasis, and a molecular target for developing a therapeutic modality for the treatment of refractory cancers." (PMID 34307149, 2021). "Functional assays using siRNAs demonstrated that knockdown of ITGA6 and ITGB1 suppressed cancer cell malignant phenotypes, especially cell migration and invasive abilities." (PMID 34199886, 2021). "Previous studies showed that several miRNAs (e.g., miR-29, miR-124-3p, miR-150, miR-218 and miR-199) directly controlled expression of ITGA6 and ITGB1 in several cancers." (PMID 34199886, 2021). "Upregulation of the metabolic genes (ALDH18A1, CAD, CHKA, POLD4, PSPH, and SQLE) and aberrant expression of cancer-related genes (ALCAM, ITGA6, DDIT3, MAP3K6, and PAK1) were found in mouse fed with high-fat-high-cholesterol similar to human NASH-HCCs." (PMID 31795276, 2019). "Laminin-332 can interact with two types of integrins, ITGA6/ITGB4 (α6β4) and ITGA3/ITGB1 (α3β1), and activation of laminin-332-mediated integrin signalling enhances cancer cell development and metastasis." (PMID 29423074, 2018). "We demonstrated for the first time the aberrant expression of cancer-related genes (ALCAM, ITGA6, DDIT3, MAP3K6 and PAK1) and metabolism-related genes (ALDH18A1, CAD, CHKA, POLD4, PSPH, SQLE and CFD) in human NASH-HCCs." (PMID 30367044, 2018).
cancer (continued). "We previously found that downregulation of miR-29 family and overexpression of laminin (LAMC2) and integrin (ITGA6) in HNSCC cells, thereby activating cancer cell migration and invasion." (PMID 29423074, 2018). "Knockdown assays using siRNAs showed that ITGA3, ITGA6 and TNC acted as cancer promoting genes in HNSCC cells." (PMID 28415821, 2017). "Our large cohort study using TCGA datasets indicated that the expression levels of ITGA3, ITGA6, and TNC were upregulated in cancer tissues." (PMID 28415821, 2017). "Among 5 genes, we focused on ITGA3, ITGA6, and TNC genes because aberrant integrin-mediated signalling promoted cancer cell aggressiveness according to our previous studies." (PMID 28415821, 2017). "Despite accumulating evidence that higher CD49f expression correlates with CSC activity and decreased survival in several cancer types, little is known about how ITGA6 gene expression is regulated." (PMID 27001172, 2016). "Most importantly, ITGA6 and SDC1 were highly expressed in HeLa and OVSAHO cancer cells." (PMID 39271776, 2024). "The upregulation of CD44 and the downregulation of ITGA6 in TPCS also suggested a stem‐like phenotype, which may contribute to its ability to generate diverse cancer cell progeny." (PMID 38582099, 2024). "In addition, ITGA6 is directly regulated by hypoxia‐inducible factor (HIF) and high ITGA6 expression enhances invasion of cancer." (PMID 37392167, 2023). "The combination of CDCP1 and ITGA6 proteins may differentiate between OVCA and non-cancer groups with a higher AUC value (0.9653) than CDCP1 alone." (PMID 37469398, 2023). "For example, integrin α6β4 has been introduced as an inhibitor of cancer metastasis in some studies, while ITGA6 antibodies do not prevent the migration phenotype of melanoma cell lines." (PMID 37444576, 2023). "Furthermore, miR-150 regulates cancer cell migration by affecting multiple effectors including matrix metalloproteinases (MMP14 and MMP13), cell adhesion molecules (ITGA3, ITGA6), transcription factors (MYB), and epigenetics factors (HMGA2 and EZH2)." (PMID 37924077, 2023). "Both ITGA6 and ITGB3 are dominantly expressed in cluster 4, and considering that they are documented as specific cancer markers, it implied that cluster 4 originates from cancer cells." (PMID 37040507, 2023). "Exercise-based approaches have recently been shown to impact the rno-miRNA-regulated target cancer gene candidates ITPR3, SOCS6, ITGA6, and NKX2-1 as biomarkers for cancer prognosis in rheumatoid arthritis diagnoses in pristane-induced arthritis (PIA) rat models." (PMID 36012617, 2022). "In addition, according to the results from our 24 pairs of cancer and adjacent-tissue samples, the expression levels of TSC1, MET, and ITGA6 in cancer were significantly higher than those in adjacent normal tissues." (PMID 36261830, 2022). "Furthermore, we found that some ITGs such as ITGA3, ITGA6 ITGA11, ITGB4, ITGB6, etc. were frequently upregulated in human cancers, whereas ITGs including ITGA1, ITGA7, ITGA8, ITGA9 and ITGB3, etc. were usually downregulated." (PMID 34222028, 2021). "Expression of ITGA6 and ITGB1 was detected in the cancer cells." (PMID 34199886, 2021). "Given that cancer cell clusters in pLN+ OSCC are ‘TGF‐βI positive’ with enriched EMT functions, we speculate that TGF‐βI is involved in upregulating EMT by inducing the marker genes in these subclusters, such as COL17A1, ITGA6 and CDH13." (PMID 40038875, 2025). "Notably, none of these pairs have been directly associated with TGFβ signaling or EMT, although many of the identified ligands (e.g., LAMC2) or receptors (e.g., CD151, COL17A1, ITGA2, ITGA3, ITGA6, ITGB1, and ITGB4) occur frequently in the context of EMT and/or cancer." (PMID 36755019, 2023).
cancer (continued). "Epithelial cell adhesion molecule (EpCAM)high integrin subunit alpha 6 (CD49f)+ luminal progenitors (LPs) and EpCAMlow/−CD49f+ basal cells (BCs) were isolated from reduction mammoplasty samples from 3 cancer-free non-carriers or prophylactic mastectomies obtained from 3 BRCA1-mutant donors." (PMID 35459234, 2022).